NIPSNAP1 (nipsnap homolog 1)
Description:
Protein involved in mitophagy by facilitating recruitment of the autophagy machinery required for clearance of damaged mitochondria. Accumulates on the mitochondria surface in response to mitochondrial depolarization and acts as a 'eat me' signal by recruiting proteins involved in selective autophagy, such as autophagy receptors (CALCOCO2/NDP52, NBR1, SQSTM1/p62, TAX1BP1 and WDFY3/ALFY) and ATG8 family proteins (MAP1LC3A, MAP1LC3B, MAP1LC3C, GABARAP, GABARAPL1 and GABARAPL2).
Tractability: PROTAC: UniProt records ubiquitination sites on it; ubiquitination databases record sites on it; its protein half-life has been measured.
Gene: Protein-coding gene on chromosome 22 (29,554,808 to 29,581,327, reverse strand). Ensembl gene ENSG00000184117.
Subcellular location: Mitochondrion matrix
Gene Ontology:
Molecular function: protein binding; protein-macromolecule adaptor activity
Biological process: mitophagy; sensory perception of pain
Cellular component: mitochondrial matrix; mitochondrion; membrane; synaptic membrane
Genetic constraint (gnomAD): Loss-of-function variants: 25 observed, 51.49 expected, observed/expected ratio (o/e) 0.49, 90% interval 0.35 to 0.68. The upper end of that interval is the gene's LOEUF score, 0.68, which puts it in group 2 of 6, group 1 being the genes least tolerant of losing a copy. Missense variants: 294 observed, 361.99 expected, observed/expected ratio (o/e) 0.81, 90% interval 0.74 to 0.89. Synonymous variants: 143 observed, 141.33 expected, observed/expected ratio (o/e) 1.01, 90% interval 0.88 to 1.16.
Homologues: Orthologues: chimpanzee NIPSNAP1 (99% identical), macaque NIPSNAP1 (99% identical), pig NIPSNAP1 (95% identical), rabbit NIPSNAP1 (95% identical), guinea pig NIPSNAP1 (94% identical), mouse Nipsnap1 (94% identical), rat Nipsnap1 (90% identical), tropical clawed frog nipsnap1 (81% identical), zebrafish nipsnap1 (67% identical), Drosophila melanogaster Nipsnap (44% identical), Caenorhabditis elegans K02D10.1 (37% identical). Paralogues in human: NIPSNAP2 (69% identical), NIPSNAP3B (22% identical), NIPSNAP3A (21% identical).
Diseases named in the same sentence as NIPSNAP1 in open-access papers:
NIPSNAP1 is named in the same sentence as 8 diseases in open-access papers, as found by Europe PMC text mining. Sharing a sentence is not in itself a finding about the gene and the disease. The quoted sentences say what the papers report.
colitis (1 paper, 2025). Inflammation of the colon. "NIPSNAP1 knockdown fails to rescue colitis-induced alterations in mitochondrial bioenergetic function." (PMID 41282096, 2025).
memory impairment (1 paper, 2020). "Slc25a5 and Nipsnap1 play prominent roles in signal transduction and postsynaptic density function regulation, therefore, the abnormal expression of these genes can result in memory impairment." (PMID 33221746, 2020).
cancer (3 papers, 2021 to 2023). A tumor composed of atypical neoplastic, often pleomorphic cells that invade other tissues. "Functional investigations revealed the knockdown of NIPSNAP1 in cancer cells induced cell cycle arrest and inhibited proliferation with the underlying phenotype resulting from senescence." (PMID 37340421, 2023). "Taken together, these results suggested that NIPSNAP1 functions to promote cancer cell proliferation while interfering with its expression appears to invoke cell cycle arrest." (PMID 37340421, 2023). "Together these data establish that NIPSNAP1 plays an important role in cancer cell homeostasis via stabilization of the c-Myc protein, with a negative feedback loop formed between c-Myc and NIPSNAP1 acting to modulate their respective expression." (PMID 37340421, 2023). "Subsequent experiments revealed that NIPSNAP1 promotes cancer cell proliferation and inhibits P27-dependent induction of senescence via dual mechanisms." (PMID 37340421, 2023). "On this basis we decided to focus on understanding how NIPSNAP1 contributes to the serum deprivation responses of cancer cells." (PMID 37340421, 2023). "Together these findings reveal an important role for NIPSNAP1 as a negative regulator of cancer cell senescence, which functions to sustain the viability of cancer cells under growth factor deprivation stress." (PMID 37340421, 2023). "Indeed, targeting NIPSNAP1 effectively impacts c-Myc levels in cancer cells, decreases cell proliferation, and induce cell cycle arrest with accompanying induction of cellular senescence." (PMID 37340421, 2023). "Importantly, the actions of NIPSNAP1 in promoting cancer cell proliferation and preventing senescence were recapitulated in vivo using xenograft models." (PMID 37340421, 2023). "Finally, we examined the projected clinical impact of NIPSNAP1 on cancer progression by investigating the effects of NIPSNAP1 expression on the growth of tumor xenografts." (PMID 37340421, 2023). "Moreover, the second distinct NIPSNAP1 pathway involved in maintaining ROS homeostasis provides a further mechanistic opportunity to drive cancer cells into a senescent state." (PMID 37340421, 2023). "Here, we alternatively identified NIPSNAP1 in a proteomics screen seeking to identify factors essential for the survival of cancer cells subjected to serum deprivation stress, a scenario that recapitulates loss of growth factor signaling within the tumor microenvironment." (PMID 37340421, 2023).
tumor (3 papers, 2022 to 2023). "Lung colonization and tumor formation experiments with cells injected into the tail vein confirmed that 2B‐HH cells, including 2B‐HH cells in which NIPSNAP1 was knocked out, could form tumors in the lungs." (PMID 36871154, 2023). "HSPA4, SPTB and NIPSNAP1 in tumor biopsies and/or their optional combinations might be potential predictive markers for nCRT response in patients with LARC." (PMID 35292026, 2022). "After four weeks, comparison of final tumor weights together with tracking of tumor volumes indicated that NIPSNAP1 knockdown significantly reduced xenograft growth relative to the controls whereas ectopic NIPSNAP1 expression resulted in significantly increased growth." (PMID 37340421, 2023). "These are preliminary results based on a small cohort, however, the results suggest that the tumor tissue-derived proteins (HSPA4, SPTB and NIPSNAP1) and a combination of HSPA4 and SPTB, could achieve relatively high predictive ability for nCRT sensitivity." (PMID 35292026, 2022).
NIPSNAP1 also shares sentences with these, for which no sentence is quoted: cervical cancer (1 paper); melanoma (1); neurodegenerative disease (1); non-small cell lung carcinoma (1).